CRP (C-reactive protein)
Diseases named in the same sentence as CRP in open-access papers (continued):
Sharing a sentence is not in itself a finding about the gene and the disease.
Crohn disease (continued). "In our study, we found positive correlations between serum elafin and CRP and fecal calprotectin only in patients with Crohn’s disease." (PMID 36552023, 2022). "In Crohn’s disease, CRP levels are perceived as unreliable in the postoperative period because of the underlying inflammatory process." (PMID 35055369, 2022). "Fatigue was rated using the fatigue visual analogue scale (fVAS) and disease activity with faecal calprotectin, C-reactive protein and the Simple Endoscopic Score for Crohn’s disease." (PMID 33940970, 2021). "Crohn’s disease CRP level-based prediction has better performance than in the UC case, but still with average ability." (PMID 34682868, 2021). "Some of the latest studies show good correlations between ultrasound parameters and inflammation markers (C-reactive protein, fecal calprotectin) and clinical severity scores of Crohn’s disease." (PMID 34377195, 2021). "Schneider showed that, in patients with Crohn disease (CD) and ulcerative colitis (UC), CRP was positively correlated with serum Cu and the Cu/Zn ratio in both CD and UC." (PMID 34684579, 2021). "Then, CAR became a novel inflammation marker with predictive value in patients with acute pancreatitis and active Crohn’s disease; it was believed to more specific than CRP or albumin alone." (PMID 34726101, 2021). "The nomogram for MH included four independent factors: baseline Crohn’s Disease Endoscopic Index of Severity, CRP at week 2, B1, and disease duration." (PMID 34567565, 2021). "Systemic low-grade inflammation caused by bacterial infections, injuries, tissue necrosis, gastrointestinal diseases (e.g. Crohn’s disease), or acute pancreatitis can be reliably detected by CRP." (PMID 33793597, 2021). "In general, fecal calprotectin (CALP) correlated more closely with the simple endoscopic score for Crohn’s disease (SES-CD) than C-reactive protein (CRP) levels, white blood cell (WBC) counts, and Crohn’s Disease Activity Index (CDAI)." (PMID 34804121, 2021). "The CRP/Alb ratio has also been reported to be a new and promising biomarker to show activity in Crohn's disease." (PMID 30522831, 2020). "In Crohn`s disease, FC (cut-off: ≥ 70 μg/g) performed more accurately in the identification of endoscopically active disease (overall accuracy: 87%) than elevated CRP, blood leukocytosis, and CDAI (overall accuracy: 66%, 54%, and 40%, respectively)." (PMID 32498475, 2020). "In this study, we used C‐reactive protein (CRP) and fecal (f‐) calprotectin (established markers) and serum albumin (explorative marker) as distinct markers of inflammatory activity in Crohn's disease patients on maintenance treatment." (PMID 32514446, 2020). "Generally, C-reactive protein (CRP) is reported to be less sensitive in UC cases, and it mildly increases in UC than in Crohn’s disease (CD)." (PMID 32245401, 2020). "One of these was a patient with known Crohn’s disease whose level was 32 μmol/L, so their CRP result was excluded from further analysis." (PMID 32731485, 2020). "Participants (n = 401) were individuals with active (C-reactive protein [CRP] measurement of ≥5 mg/L at enrollment) Crohn disease who received ustekinumab therapy." (PMID 31074823, 2019). "It is an objective indicator of inflammation, and CRP levels have been shown to correlate well with clinical disease activity in gastrointestinal diseases such as Crohn's disease and AP." (PMID 31114724, 2019). "Random forest methods were used in building 2 models for predicting Crohn disease remission, with a CRP level lower than 5 mg/dL as a proxy for biological remission, beyond week 42 of ustekinumab treatment." (PMID 31074823, 2019). "C-reactive protein (CRP) is elevated as an inflammatory marker in response to infections and inflammation (such as Crohn’s disease or neoplasia), but it cannot be distinguished between immediate and non-urgent causes alone." (PMID 31633098, 2019).
Crohn disease (continued). "My initial measurements of serum CRP concentration in 1975 swiftly showed that CRP was an excellent marker of Crohn's disease, closely reflecting extent and activity much better that any other single measurement." (PMID 30459761, 2018). "Correlations between the Lewis score and abbreviated Pediatric Crohn's Disease Activity Index, C-reactive protein, and small bowel transit time in pediatric patients with small bowel Crohn's disease." (PMID 28816962, 2017). "The related clinical information included Crohn disease (CD), ulcerative colitis (UC), extent, behavior, complication, active index, Hs-CRP, ESR, platelet count, BMI, hemoglobin value, albumin levels, and CDEIS." (PMID 28538364, 2017). "We have recorded clinical (Crohn’s disease activity index, CDAI), biological (CRP, fecal calprotectin), endoscopic (Crohn’s disease endoscopic index of severity, CDEIS) markers of activity during a 6 months of follow-up." (PMID 29163522, 2017). "Relationships between the capsule endoscopy Lewis score (LS) and clinical disease activity indices and C-reactive protein (CRP) are controversial in adult patients with Crohn's disease (CD)." (PMID 28816962, 2017). "Crohn’s disease patients in clinical remission were more frequently in CRP-based remission, compared to patients with active disease." (PMID 27573259, 2016). "IFX therapy decreased Pediatric Crohn's Disease Activity Index (PCDAI) scores as well as the elevated CRP levels." (PMID 27329601, 2016). "ESR was elevated with the patient reporting abdominal pain and diarrhea consistent with prior flares of her Crohn's disease; however CRP was within normal range." (PMID 25784930, 2015). "The serum IL17 levels, complete blood count, blood chemistry, erythrocyte sedimentation rate (ESR), and C-reactive protein (CRP) levels were measured, and Crohn's disease activity was calculated using Crohn's disease activity index (CDAI)." (PMID 25140070, 2014). "A 31-year-old Japanese man, who had been treated with infliximab infusions for Crohn’s disease, was referred to our hospital presenting with an abrupt onset of high fever and an elevated white blood cell count and serum C-reactive protein level." (PMID 23374532, 2013). "Patients with CD-active, reflecting a mild inflammatory state, had 10-fold higher plasma CRP levels than those with Crohn's disease in remission (P < 0.05)." (PMID 22611487, 2012). "We investigated the height, body weight, serum levels of albumin, IGF-I, CRP, and cytokines, and the amount of corticosteroid administered in children with Crohn's disease (CD, n = 15) and ulcerative colitis (UC, n = 18)." (PMID 20454571, 2010). "However, when analysing the AUC for CRP and fibrinogen levels, statistically significant values were obtained, indicating a significant discriminatory ability regarding the patient’s Crohn’s disease activity in both IFX and ADA groups." (PMID 41470167, 2025). "Secondary outcomes were quality of life (QoL) (IBDQ-9), disease activity (CDAI for Crohn’s disease, partial Mayo score for ulcerative colitis), and biochemical markers (CRP, faecal calprotectin)." (PMID 40362901, 2025). "Some clinical and serological parameters, including Crohn’s Disease Activity Index (CDAI), CRP levels, ESR, ALB levels, neutrophil to lymphocyte ratio (NLR), platelet to lymphocyte ratio (PLR), and CRP to ALB ratio (CAR), are reported associated with MH in patients with CD." (PMID 40630487, 2025). "The CALM trial randomised 244 adults with Crohn's disease (mean duration 1 year) and endoscopic activity to tight control (treatment escalation for elevated CRP or calprotectin as well as symptoms) versus conventional management (treatment escalation for symptomatic flares)." (PMID 38402895, 2024). "Clinical disease activity (Harvey–Bradshaw-index (HBI) in Crohn’s disease (CD), partial Mayo score (pMS) in ulcerative colitis (UC)), CRP, TL, ADA, therapy-discontinuations and (serious) adverse events ((S)AE)) were monitored throughout the study." (PMID 39619829, 2024).
Crohn disease (continued). "Moreover, as the median CRP concentration in the blood of patients with Crohn’s disease was increased compared to the reference values, we estimated the correlation between the level of this inflammatory marker and serum profiles of pro-GN, PTX3 and S100A12." (PMID 37892129, 2023). "At week 6, less than half the participants (46.5% on SCD and 43.5% on Mediterranean diet) were in remission using the short Crohn's disease activity index, less than 35% of participants had a faecal calprotectin <250 μg g–1 and less than 5% had high‐sensitivity CRP < 5 mg L–1." (PMID 35735908, 2023). "Low vitamin D was associated with partial Mayo scores and C‐reactive protein (CRP) to albumin ratio in ulcerative colitis, and CRP and CRP/albumin ratio in Crohn's disease." (PMID 38162852, 2023). "CRP is also used to predict prognosis and relapse of Crohn's disease." (PMID 37476185, 2023). "However, serum C-reactive protein levels, disease duration, and the presence of an ileocolonic Crohn’s disease phenotype were found to be significantly and independently positively related to LPL." (PMID 36982268, 2023). "In fact, it is suggested that CRP is a fairly sensitive biomarker for Crohn’s disease." (PMID 37685662, 2023). "In conclusion, our results suggest that AIF-1 could be a complementary biomarker of CRP to monitor the severity of Crohn’s disease." (PMID 35327530, 2022). "In order to check whether the expression of CRP and SSA was affected by rs7158663 and rs322931 polymorphisms, the abundance of CRP and SSA protein in the peripheral blood of patients of Crohn’s disease was measured using ELISA." (PMID 35422450, 2022). "The study revealed Crohn’s Disease was correlated with coagulation initiated by increased IL-1 levels, whereas Ulcerative Colitis was correlated with increased levels of C-reactive protein (CRP)." (PMID 36278572, 2022). "The 8-week EEN resulted in a remission of the condition of subjects with active CD, as revealed by a significant decrease in erythrocyte sedimentation rate (ESR) (P = 0.018), C-reactive protein (CRP) (P = 0.028), and Crohn’s disease activity index (CDAI) (P = 0.018)." (PMID 35501724, 2022). "Primary outcome measures were change of disease activity [Harvey-Bradshaw Index for Crohn’s disease (CD), partial Mayo Score for ulcerative colitis (UC)], C-reactive protein (CRP), infliximab trough levels (TLs), anti-drug antibodies (ADAs) and adverse events." (PMID 33505519, 2021). "IGF-1 values declined as CRP increased, consistent with observations from a previous Zimbabwean birth cohort, and suggestive of growth hormone resistance due to chronic inflammation, as is seen in clinical disorders such as Crohn’s disease." (PMID 32059011, 2020). "In addition, BAE findings have shown a poor correlation between endoscopic lesions and the Crohn’s Disease Activity Index (CDAI)/C-reactive protein (CRP)." (PMID 32130521, 2020). "A total of 876 IBD patients, composed of 275 patients with ulcerative colitis (UC) and 601 patients with Crohn's disease (CD), were included in this retrospective study, and the serum C-reactive protein (CRP), albumin (ALB), erythrocyte sedimentation rate (ESR), and CBC parameters were measured." (PMID 32655630, 2020). "Since the relationship of Crohn's disease activity to inflammatory biomarkers such as CRP may be useful in a ‘treat-to-target’ approach to biologic therapy, it will be important to further elucidate these relationships in multiple ‘subjects." (PMID 32253915, 2020). "Due to evidence of malabsorption in this patient, the differential diagnosis should also include Crohn’s disease, which can involve all parts of the gastrointestinal tract and present with increased CRP levels (as found in the discussed patient), nausea, vomiting and epigastric pain." (PMID 32468113, 2020).
Crohn disease (continued). "The present study sought to evaluate CD inflammatory activity using clinical and noninvasive laboratory markers (hemogram, C-reactive protein and faecal calprotectin) and correlate them to endoscopic findings, evaluated through the Simple Endoscopic Score for Crohn’s Disease – SES-CD." (PMID 32054445, 2020). "CRP may be a useful predictor of surgery in subgroups of patients with either UC or Crohn’s disease." (PMID 30997787, 2019). "We applied machine learning techniques to phase 3 trial data to generate predictive models of treatment response to ustekinumab at week 42 in patients with active Crohn disease, as defined by an elevated CRP level at enrollment using dichotomized CRP as a marker of biological remission." (PMID 31074823, 2019). "I assumed that CRP production would be increased in active Crohn's disease and speculated that it could be responsible for suppression of T cell function." (PMID 30459761, 2018). "In addition to CDAI and CRP levels, vitamin D levels are highly correlated with endoscopic disease activity assessed by simple endoscopic score for Crohn's disease." (PMID 29348747, 2017). "An idea of adjusting disease activity among groups using indices such as Crohn’s disease activity index (CDAI) or serum C-reactive protein level could be suggested to overcome our limitation." (PMID 28542298, 2017). "Clinical disease activity was assessed by Crohn's disease activity index and C-reactive protein." (PMID 29348747, 2017). "The aim of this study was to determine the perioperative behavior of C-reactive protein (CRP) in Crohn’s disease (CD) patients undergoing elective ileo-cecal (IC) resection and to identify association between perioperative CRP levels and endoscopic recurrence at 1 year." (PMID 27551522, 2016). "ESR level was normal; however, CRP levels were elevated which may, in addition to a recent episode of loose stool, suggest a flare of her Crohn's disease." (PMID 25784930, 2015). "Researchers have also identified several factors that may be associated with subsequent surgery, including longer disease duration, higher Crohn’s disease activity indexes, higher levels of C-reactive protein, lower levels of albumin, abscess, and bowel stricture." (PMID 40674301, 2025). "Furthermore, a significant correlation has been identified with CRP levels and with endoscopic findings and scores, such the simple endoscopic score for Crohn’s disease [SES-CD] and the Mayo score." (PMID 38792945, 2024). "However, in addition to assess high CVD risk, measurement of CRP from DBS could have clinically added value in the follow-up of e.g. rheumatoid disease, Crohn’s disease, and sarcoidosis, from the comfort of the patients home." (PMID 36781868, 2023). "Conventional measures including clinical/endoscopic activity scores (Mayo, Crohn’s Disease Activity Index) and biochemical indices (C-reactive protein, fecal calprotectin) have proved useful for monitoring patients but remain inadequate for predicting response to therapy." (PMID 35660024, 2022). "The outcome predictors in IBD trials usually include DAI, C-reactive protein (CRP), rapid fecal calprotectin (FC), the Mayo score and the Crohn’s Disease Activity Index (CDAI), and the correct interpretation of the results relies on quality preparation for colonoscopy." (PMID 34072930, 2021). "Consequently, the AUC of −25(OH)D3 in ROC analysis for Crohn's disease activity was much higher than the AUCs of CRP and ESR, which indicate that −25(OH)D3 might be a better predictor of disease activity." (PMID 30647532, 2018). "Relapse was defined as a pediatric Crohn's disease activity index (PCDAI) >12.5, Simple Endoscopic Score‐CD (SES‐CD) score >7, Lewis score > 135, and/or abnormal C‐reactive protein levels (CRP > 0.15 mg/dL)." (PMID 41532979, 2026).
Crohn disease (continued). "This study aimed to investigate the diagnostic accuracy of serum LRG concentrations in patients with Crohn’s disease (CD), and to evaluate the utility of combination use of LRG and CRP for predicting endoscopic activity." (PMID 39823192, 2025). "Similarly, AGA guidelines on the management of Crohn’s disease recommend CRP is used to guide whether endoscopic investigation is required, and the high variation of CRP could mean that a patient is classified incorrectly as requiring or not requiring endoscopy." (PMID 41284612, 2025). "Serum C-reactive protein (CRP), leucine-rich alpha-2 glycoprotein (LRG), and fecal calprotectin (Fcal) are non-invasive markers used to assess Crohn’s disease (CD) severity." (PMID 40355822, 2025). "Specifically, while CRP values showed a significant relationship with lower MDA levels, Crohn’s disease types A2 and L2 exhibited higher MDA levels compared to other phenotypes." (PMID 39456425, 2024). "We have previously shown that LBP positively correlated with CRP under inflammatory conditions (~1700 DBS samples collected during infections, vaccinations, surgery, intense exercise, and Crohn’s disease)." (PMID 39458532, 2024). "HBOT significantly reduced the level of C-reactive protein (CRP) (80.79 ± 42.05 mg/L vs. 33.32 ± 18.31 mg/L, P = 0.004) and the Crohn’s Disease Activity Index (CDAI) (274.87 ± 65.54 vs. 221.54 ± 41.89, P = 0.044)." (PMID 38816750, 2024). "In conclusion, Mann-Whitney U test showed that absolute monocyte count, PLT, absolute neutrophil count, ESR, CRP, PT, D-Dimer, TBIL, ALB, HCT, Hb were correlated with disease activity of Crohn’s disease." (PMID 38598519, 2024). "IBD, inflammatory bowel disease; CD, Crohn’s disease; UC, ulcerative colitis; ESR, erythrocytes sedimentation rate; CRP, C-reactive protein." (PMID 38658864, 2024). "After six weeks of CDED implementation, a substantial decrease in paediatric Crohn's disease activity index (PCDAI) was observed, equivalent to that of EEN, accompanied by a significant decline in C-reactive protein (CRP) levels." (PMID 37746457, 2023). "We found that Crohn’s Disease Activity Index (CDAI), C-reactive protein (CRP) and platelet-to-lymphocyte percentage ratio (PLpR) were independently associated with endoscopic activity." (PMID 37770845, 2023). "Among these, we mention clinical severity scores, such as Crohn’s disease activity index (CDAI) and the Harvey–Bradshaw index (HBI), or laboratory tests, such as faecal calprotectin or C-reactive protein (CRP) levels." (PMID 37629610, 2023). "Inflammatory markers such as C-reactive protein (CRP) and white blood cell count decreased in children and adolescents with moderate-to-severe Crohn’s disease on TNF-α inhibitor therapy." (PMID 37189883, 2023). "Clinical, biochemical, and endoscopic response and remission rate were determined by Crohn's disease activity index (CDAI), C-reactive protein (CRP) levels, and SES-CD evaluation." (PMID 37554510, 2023). "The objective of this study was to quantify the relative efficacy of investigational and approved biological treatments for CD measured in Crohn's Disease Activity Index (CDAI), Inflammatory Bowel Disease Questionnaire (IBDQ), and C-reactive protein (CRP)." (PMID 35371027, 2022). "Their median IBD duration was 7 (IQR 10) years, median CRP level was 7 (IQR 14) mg/L, and 28 (44%) had complications (fistula, stricture, bowel resection etc.), while 28 with Crohn’s disease (68%) had colonic involvement." (PMID 35817816, 2022). "They all had clinically active Crohn’s disease, based on a Crohn’s Disease Activity Index (CDAI) score greater than 150, accompanied by a raised C- reactive protein and elevated faecal calprotectin." (PMID 35054315, 2022). "ELISA was carried out to examine the expression of TNF-α, IL-1β, IL-6, CRP, SSA, AAT, AAG and HPT in the peripheral blood of patients with Crohn’s disease." (PMID 35422450, 2022).